RPL3 (ribosomal protein L3)
Description:
Component of the large ribosomal subunit. The ribosome is a large ribonucleoprotein complex responsible for the synthesis of proteins in the cell.
Synonyms: TARBP-B; L3; uL3; ASC-1
Tractability: Small molecule: an approved drug acts on it; a structure with a bound ligand is known; a high-quality ligand is known. PROTAC: UniProt records ubiquitination sites on it; ubiquitination databases record sites on it; its protein half-life has been measured; a small molecule that binds it is known. Other modalities: a drug acting on it is in phase 2 or 3 trials.
Target class: Other cytosolic protein
Gene: Protein-coding gene on chromosome 22 (39,312,870 to 39,320,389, reverse strand). Ensembl gene ENSG00000100316.
Subcellular location: Nucleus, nucleolus; Cytoplasm
Subcellular location (Human Protein Atlas): Cytosol; Nucleoli
Pathways (Reactome):
Metabolism of proteins: Eukaryotic Translation Termination; Formation of a pool of free 40S subunits; GTP hydrolysis and joining of the 60S ribosomal subunit; L13a-mediated translational silencing of Ceruloplasmin expression; PELO:HBS1L and ABCE1 dissociate a ribosome on a non-stop mRNA; Peptide chain elongation; Ribosome Quality Control (RQC) complex extracts and degrades nascent peptide; SRP-dependent cotranslational protein targeting to membrane; ZNF598 and the Ribosome-associated Quality Trigger (RQT) complex dissociate a ribosome stalled on a no-go mRNA
Metabolism of RNA: Major pathway of rRNA processing in the nucleolus and cytosol; Nonsense Mediated Decay (NMD) enhanced by the Exon Junction Complex (EJC); Nonsense Mediated Decay (NMD) independent of the Exon Junction Complex (EJC)
Cellular responses to stimuli: Response of EIF2AK4 (GCN2) to amino acid deficiency
Developmental Biology: Regulation of expression of SLITs and ROBOs
Disease: Viral mRNA Translation
Metabolism: Selenocysteine synthesis
Gene Ontology:
Molecular function: protein binding; RNA binding; structural constituent of ribosome
Biological process: cytoplasmic translation; spermatogenesis; translation
Cellular component: cytoplasm; cytosol; cytosolic large ribosomal subunit; cytosolic ribosome; extracellular exosome; focal adhesion; nucleolus; nucleus; protein-containing complex; ribosome
Genetic constraint (gnomAD): Loss-of-function variants: 3 observed, 46.9 expected, observed/expected ratio (o/e) 0.064, 90% interval 0.028 to 0.17. The upper end of that interval is the gene's LOEUF score, 0.17, which puts it in group 1 of 6, group 1 being the genes least tolerant of losing a copy. Missense variants: 387 observed, 543.71 expected, observed/expected ratio (o/e) 0.71, 90% interval 0.65 to 0.77. Synonymous variants: 224 observed, 196.93 expected, observed/expected ratio (o/e) 1.14, 90% interval 1.02 to 1.27.
Homologues: Orthologues: macaque RPL3 (100% identical), dog RPL3 (99% identical), pig RPL3 (99% identical), mouse Rpl3 (99% identical), rat Rpl3 (99% identical), chimpanzee RPL3 (98% identical), guinea pig RPL3 (98% identical), tropical clawed frog rpl3 (93% identical), zebrafish rpl3 (90% identical), Drosophila melanogaster RpL3 (75% identical), Caenorhabditis elegans rpl-3 (71% identical). Paralogues in human: RPL3L (78% identical).
Diseases named in the same sentence as RPL3 in open-access papers:
RPL3 is named in the same sentence as 47 diseases in open-access papers, as found by Europe PMC text mining. Sharing a sentence is not in itself a finding about the gene and the disease. The quoted sentences say what the papers report.
colon cancer (26 papers, 2014 to 2024). "Comparison of human lung and colon cancer specimens with patient-matched normal tissues reveals a selective downregulation of rpL3 in the cancer tissues demonstrating that rpL3 is implicated in lung and colon cancer tumorigenesis." (PMID 28085118, 2017). "For example, RPL3 is highly downregulated in colon cancer and promotes the progression of colorectal cancer cells." (PMID 39309445, 2024). "In colon cancer studies, the decreased level of the ribosomal protein universally conserved ribosomal protein L3 induces autophagy activation via the nucleolar stress pathway, thereby causing chemoresistance." (PMID 38409361, 2024). "Studies of RPL3 in a human colon cancer cell line indicate that RPL3 binds to the nuclear DNA binding protein poly ADP-ribose polymerase 1 (PARP-1) and represses the transcription of pro-invasive genes (Pecoraroet al., 2019)." (PMID 38628976, 2023). "It has recently reported that overexpression of ribosomal protein L3, which is a target of 5-FU, reduces migration and reciprocally promotes apoptosis of lung and colon cancer cells under the treatment of 5-FU." (PMID 30469446, 2018). "For example, RPL3 expression is a determinant of chemotherapy response in certain lung and colon cancers." (PMID 29530001, 2018). "The activation and overexpression of RPL3 by the chemotherapeutic drug 5-fluorouracil (5-FU) induces cell apoptosis and regresses cell proliferation in colon cancer, which suggest that the combination of RPL3 and 5-FU could be a novel therapy in colon cancer." (PMID 34873618, 2021).
colon cancer (continued). "This is supported by the fact that the absence of uL3, the cross-domain name of RPL3, can induce chemoresistance by increasing autophagic flux in colon cancer cells." (PMID 34873618, 2021).
lung carcinoma (9 papers, 2016 to 2025). "RPL3 also associates with the high-risk neuroblastoma subtype and may have a role in the acquisition of lung cancer multidrug resistance." (PMID 29530001, 2018). "As a newly identified CBS and NFκB repressor, we suggest that rpL3 could be used in association with 5-FU to enhance the susceptibility of lung cancer cells to this drug." (PMID 27924828, 2016). "In the lung cancer cell line Calu‐6 after 5‐FU treatment, rpL3 decreased its stability at transcriptional and post‐translational levels by targeting CBS to enhance the effect of 5‐FU on cancer cells' lethality." (PMID 36929586, 2023). "In lung cancer tissues, the expression of rpL3 was down‐regulated and the expression of CBS was up‐regulated." (PMID 36929586, 2023). "Ribosomal proteins (rp) play a key role in the therapeutic effects of 5‐FU on tumours, and rpL3 is a key sensing molecule for 5‐FU and oxaliplatin‐induced ribosomal stress in colon and lung cancers." (PMID 36929586, 2023). "Our results suggest a more ubiquitous role for RPL3 in regulating tumor phenotypes, beyond that already described in colorectal carcinoma, lung cancers, and neuroblastoma." (PMID 29530001, 2018). "All together these results strongly suggest that the ectopic expression of rpL3 allowed a more potent cytotoxic activity of 5-FU on lung cancer cells." (PMID 27924828, 2016). "Having established the expression profile of CBS and rpL3 in tumors we became interested to investigate the possible involvement of rpL3 in the control of CBS expression in lung cancer treatment." (PMID 27924828, 2016). "To evaluate CBS and rpL3 clinical significance in lung cancer, we employed quantitative real-time PCR (qRT-PCR) and immunoblotting to assess the expression of CBS and rpL3 at the mRNA and protein levels in 21 lung cancers and normal tissues." (PMID 27924828, 2016). "Besides, the restoration of RPL3 protein may resensitize the resistant cells to the drug by regulating the reactive oxygen species (ROS) levels in lung cancer cells." (PMID 29687002, 2018). "Comparison of human lung cancer specimens with patient-matched normal tissues revealed the up-regulation of CBS and the down-regulation of rpL3 in the cancers." (PMID 27924828, 2016). "In particular, we demonstrated that human rpL3 acts as stress sensing molecule essential for cancer cell response to ribosomal stress caused by 5-FU and oxaliplatin (L-OHP) in colon and lung cancer cells lacking active p534." (PMID 27924828, 2016).
breast carcinoma (4 papers, 2015 to 2024). "In our study, the loss of RPL3 and defects in its methylation inhibited p-Src levels, reducing the metastatic capacity of breast cancer cells." (PMID 39309445, 2024). "In conclusion, we demonstrated that the generation of biphosphorylated Src by a METTL18-driven RPL3/HSP90/actin/Src sequential pathway significantly contributes to the metastasis of HER2-negative breast cancer." (PMID 39309445, 2024). "Four of the ten late-type genes, the ribosome-related factors EIF4B, RPL5, RPL3, and the tumor angiogenesis modifier EPN3 were significantly associated with MFS in the late period also in a meta-analysis of tamoxifen-treated breast cancer cohorts." (PMID 27926932, 2016). "One late-type gene (EPN3) was significantly associated with shorter OS, and two late-type genes (RPL3, EIF4B) with longer OS, in more than one cohort, in agreement with findings in breast cancer." (PMID 27926932, 2016). "However, the role of RPL3 in breast cancer and its action mechanism are poorly understood." (PMID 39309445, 2024). "Furthermore, as evident from S7B–S7D Table, several late-type genes showed a significant, but opposite, association with prognosis in one or more cohorts compared to the initial analysis of breast cancer, exemplified by RPL10, EIF4B, GPBP1L1 in NSCLC and RPL3, RPS6 and STEAP1 in ovarian cancer." (PMID 27926932, 2016). "Three late-type genes, EIF4B, RPL5 and RPL3, were found to be significantly associated with late metastasis in two or more cohorts, all associated with longer MFS in the univariate Cox analysis, in agreement with findings in the node-negative, untreated breast cancer cohorts." (PMID 27926932, 2016).
colorectal cancer (4 papers, 2018 to 2024). A primary or metastatic malignant neoplasm that affects the colon or rectum. "As with RPL3, deregulated RPS4X has been previously associated with various tumors and tumor phenotypes, including subgroups of colorectal carcinoma, a myelodysplasia risk signature and poor prognosis in bladder cancer." (PMID 29530001, 2018). "Moreover, RPL3 interacts with DUOX2 that promotes the progression of colorectal cancer cells." (PMID 38925865, 2024). "In colorectal cancer cells, knockdown of DUOX2 inhibits invasion and migration that can be reversed by the overexpression of RPL3." (PMID 38925865, 2024).
diabetes (4 papers, 2017 to 2026). "First, we selected the central core sites in the PPI network of AS, DN, DR and found six characteristic genes of diabetes (TYROBP, LCP2, CCL2, CD44, RPL3, CDK4)." (PMID 36755923, 2023). "Drugs closely related to diabetes, such as Fenretinide, Dimethylamine parthenolide, Chelerythrine, etc., have obvious positive correlation with LCP2, TYROBP, RPL3, CDK4, and CD44." (PMID 36755923, 2023).
COVID-19 (2 papers, 2022 to 2024). A disease caused by infection with severe acute respiratory syndrome coronavirus 2. "Also, spec_24h mRNAs were enriched in 12 KEGG terms such as Coronavirus disease-COVID-19, Ribosome, MAPK signaling pathway, Cytokine-cytokine receptor interaction, Focal adhesion, involving genes such as Rpl7, Rpl3, Rpl5, Rpl4, Rps15a." (PMID 38622534, 2024).
glioma (2 papers, 2023 to 2024). A benign or malignant brain and spinal cord tumor that arises from glial cells (astrocytes, oligodendrocytes, ependymal cells). "In the intricate landscape of glioma pathogenesis, the elucidation of risk scores derived from pivotal hub genes—RPL3, RPL12, PTEN, IFNGR2, KLF10, PLAUR, MSN, and IKBIP—emerged as a critical component in understanding the disease’s progression and patient stratification." (PMID 38137116, 2023).
heart failure (2 papers, 2023 to 2024). Inability of the heart to pump blood at an adequate rate to meet tissue metabolic requirements. "However, the re-expression of RPL3 was somewhat more variable at 12 weeks of TAC likely due to variation in the degree of heart failure in each of these mice." (PMID 36733907, 2023).
influenza (2 papers, 2021 to 2023). An acute viral infection of the respiratory tract, occurring in isolated cases, in epidemics, or in pandemics; it is caused by serologically different strains of viruses (influenzaviruses) designated A, B, and C, has a 3-day incubation period, and usually lasts for 3 to 10 days. "RPS26 and RPL3 are ribosomal proteins (RP) and both are related to influenza viral RNA transcription and replication." (PMID 35186014, 2021). "RPL3 and EEF1G, which enable different ribosomal-related enzyme functions, are commonly downregulated during initial acute influenza infection." (PMID 37533854, 2023).
thyroid cancer (2 papers, 2018 to 2023). "Three CRG models (FDX1, BUB1, RPL3) could better predict the prognosis of thyroid cancer." (PMID 37745716, 2023). "Compared with normal thyroid tissue, 7 CRGs were more highly expressed in thyroid cancer, namely BUB1 (P<0.001), RPL3 (P<0.001), TTK (P<0.001), GINS2 (P<0.001), SLC26A6 (P<0.001), CDKN2A (P<0.001) and ZNHIT2 (P<0.001)." (PMID 37745716, 2023). "The three-gene model (FDX1, BUB1, RPL3) was constructed to predict DFS of 1, 3 and 5 years in thyroid cancer (AUC: 0.789, 0.733, 0.757)." (PMID 37745716, 2023).
atrial fibrillation (1 paper, 2018). A disorder characterized by an electrocardiographic finding of a supraventricular arrhythmia characterized by the replacement of consistent P waves by rapid oscillations or fibrillatory waves that vary in size, shape and timing and are accompanied by an irregular ventricular response. "The RPL3L missense variant associating with atrial fibrillation is p.Ala75Val, and Ala75 is highly conserved in both RPL3L and RPL3 over a range of species (PROVEAN impact prediction scores <−2.520)." (PMID 30271950, 2018).
brain cancer (1 paper, 2018). A primary or metastatic malignant neoplasm affecting the brain. "Many clusters of tumors with down-regulated RPL3, including HCC, kidney clear cell cancer, and brain cancer, possessed inferior survival." (PMID 29530001, 2018).
breast tumour (1 paper, 2011). "In publically available data sets, interrogated using Oncomine, RPL3 was downregulated: two-fold in ovarian adenocarcinoma compared with normal ovary (P-value 6.94 × 10−10), and 36-fold in breast tumour stroma compared with normal stroma (P-value 1.06 × 10−28)." (PMID 21407217, 2011).
chronic myeloid leukemia (1 paper, 2018). "Moreover, RPL3 is involved in modulation of cell cycle and apoptosis pathways and serves as a target of Omacetaxine, an anticancer drug used for chronic myeloid leukemia." (PMID 30557369, 2018).
liver cancer (1 paper, 2022). An epithelial or non-epithelial malignant neoplasm that arises from the liver. "Above results demonstrated the rationality of RPL3 inhibition for treating liver cancer." (PMID 35191375, 2022). "In addition, leveraging CRISPR-based screening data from Project Achilles, we found that RPL3 was essential for maintaining the survival and growth of all liver cancer cell lines." (PMID 35191375, 2022).
liver fibrosis (1 paper, 2026). "Histological analysis revealed a higher severity of liver injury in Rpl3‐K393R‐transduced mice, characterized by the disrupted hepatic lobular architecture, a marked aggregation of inflammatory cells, and pronounced liver fibrosis." (PMID 41114463, 2026).
lung adenocarcinoma (1 paper, 2019). A carcinoma that arises from the lung and is characterized by the presence of malignant glandular epithelial cells. "RPL3, HSP90AA1, ATAD2, and PIAS1 as well as USP25, which is targeted by miR-200b, miR-200c, and miR-429, may be the potential targets of HPD in lung adenocarcinoma." (PMID 30717818, 2019). "RPL3, HSP90AA1, ATAD2, as well as PIAS1 and USP25, which is targeted by miR-200b, miR-200c, and miR-429 may show correlations with the sensibilization effect of HPD in lung adenocarcinoma." (PMID 30717818, 2019).